EGFR (epidermal growth factor receptor)
Diseases named in the same sentence as EGFR in open-access papers (continued):
Sharing a sentence is not in itself a finding about the gene and the disease.
tumor (continued). "In cancer, eccDNA often carries oncogenes such as MYC, EGFR, and CDK4, enabling their overexpression and contributing to tumor progression 20,63,160." (PMID 40521196, 2025). "Factors like patient age, tumor size, tumor-node-metastasis (TNM) stage, epidermal growth factor receptor (EGFR) status, treatment choices can all impact the prognosis of GSRC." (PMID 41333052, 2025). "DCA, a secondary BA produced by Clostridium sordellii, enhances EGFR activation and stimulates PI3K/AKT/mTOR signaling, leading to increased tumor cell proliferation, invasion, and angiogenesis through upregulation of VEGF mRNA." (PMID 40959527, 2025). "Targets specific molecules (e.g., EGFR, VEGF) to inhibit tumor growth, with relatively fewer side effects." (PMID 41551160, 2025). "In breast cancer, inflammatory cytokine networks, especially ILs and TNF, enhance immune infiltration and metastasis, with SPINK overexpression contributing to EGFR and Akt pathway activation, driving EMT and tumor progression." (PMID 40872585, 2025). "Curcumin has been shown to inhibit protein synthesis in tumor cells by modulating the activity of key proteins, including CDK2, CK2α, GSK3β, DYRK2, and EGFR." (PMID 41515171, 2025). "Even within the same primary tumor, not all cells may have the activating EGFR mutation." (PMID 40647400, 2025). "These mediators include RTKs like EGFR and FGFR, as well as tumor cell survival pathways like AXL, PI3K, or CDK4/6." (PMID 40940900, 2025). "SAMiRNA-AREG specifically silences AREG mRNA, effectively reducing both EGFR-dependent and TGF-β signaling in fibrotic and tumor tissues." (PMID 40725192, 2025). "Copy number gain (CNG) of EGFR analysed by FISH is detected in around 20% and EGFR is overexpressed in around 50% of tumours." (PMID 40615716, 2025). "Research indicates that EGFR-TKI treatment can induce autophagy in various tumor cells, potentially leading to tumor resistance." (PMID 40303296, 2025). "To investigate the clinical relevance of EGFR, EpCAM, TF, and TROP2 expression, we stratified TNBC tissue samples by tumor stage (I–III), histological grade (G1–G3), and patient age and assessed marker distribution via mIF analysis." (PMID 40806559, 2025). "Increased levels of cytokines such as IL-6, IL-8, and TGF-β promote EGFR TKI resistance and tumor progression." (PMID 40002883, 2025). "EGFR inhibitor erlotinib with anti-VEGF antibody bevacizumab, in combination with radiation therapy, showed remarkable tumor inhibition in a xenograft model." (PMID 41511327, 2025). "Overall, the observed changes in growth rate support the critical involvement of EGFR and IGF-IR in sustaining tumor cell proliferation under 3D conditions." (PMID 40943584, 2025). "further demonstrated that dual engineering of NK cells with an EGFR vIII-targeted CAR and the CXC chemokine receptor 4 (CXCR4) augmented tumor infiltration capacity, thereby improving therapeutic outcomes in solid tumor models." (PMID 41181137, 2025). "For EGFR-driven NSCLC, nanocarrier-assisted PROTAC delivery significantly enhanced in vivo antitumor efficacy in resistant xenografts, while co-delivery of EGFR and BRD4 degraders in a single nanoplatform achieved synergistic tumor suppression." (PMID 41008623, 2025). "Inhibition of EGFR allowed TET1 to bind to tumor suppressor promoters, reactivating their expression via DNA demethylation and significantly inhibiting tumor growth." (PMID 40520993, 2025). "PD‐L1 and PD‐L2 expression levels were assessed using tumor proportion score (TPS) and combined positive score (CPS), whereas EGFR was evaluated using the H‐score." (PMID 40156197, 2025). "ERRFI1, as a feedback suppressor of EGFR and ERBB2, is regulated by NAT10 in an ac4C-dependent manner, participates in the EGFR-mediated signaling pathway, and participates in tumor development and chemotherapy resistance in CRC." (PMID 41316475, 2025).
tumor (continued). "In CRC, signaling pathways mediated by both EGFR and TLR play crucial roles in promoting tumor growth, survival, and metastasis." (PMID 41419456, 2025). "Mechanistically, laminin-5 interacts with integrin α6β4 and EGFR, triggering the activation of phosphatidylinositol-3-kinase (PI3K), a signalling pathway that governs tumor proliferation, invasion, and apoptosis evasion." (PMID 40621224, 2025). "EGFR, a key upstream regulator of the MAPK/ERK signaling cascade, promotes tumor cell migration and invasion." (PMID 40259338, 2025). "The tumor microenvironment also fosters EMT by creating a conducive setting for cancer cell survival and proliferation, ultimately mediating resistance to EGFR-TKIs in NSCLC." (PMID 40003951, 2025). "The CLSM examination of tissue treated with Anti-EGFR-GNPs-FITC demonstrates effective distribution and bioconjugation of Anti-EGFR-GNPs-FITC within tumor cells." (PMID 41367681, 2025). "Later, a pooled analysis of RCTs confirmed the predictive value of primary tumor location, and the recent Japanese PARADIGM trial prospectively showed improved OS with anti-EGFR therapy compared to BEV, particularly in left-sided tumors." (PMID 39941768, 2025). "BRD4 inhibition with JQ1 disrupted immunosuppressive gene activation, and its combination with EGFR CAR-T therapy reduced immunosuppression, effectively curbing tumor growth and metastasis in GBM xenografts." (PMID 40565099, 2025). "As expected, simultaneous inhibition of EGFR and MET with Afatinib and Capmatinib in the presence of EGF and HGF, results in an almost complete cessation of tumor cell invasion in 3D." (PMID 41115375, 2025). "If the gene test result of biopsy tissue is EGFR wild type but the prediction result of this model is EGFR mutation, clinicians may be alerted to the possibility of false negative results due to tumor heterogeneity in the biopsy, necessitating an evaluation of the need for a re-biopsy." (PMID 40969259, 2025). "It is well established that the ErbB family of receptors, including EGFR, human epidermal growth factor 2 (HER2), HER3, and HER4, stimulate tumor progression in many cancer types." (PMID 40857406, 2025). "Advances in GBM therapeutics have introduced novel approaches, including targeted therapies (e.g., EGFR inhibitors), immunotherapies such as ICIs and CAR-T cell therapies, and noninvasive modalities such as the tumor-treating field (TTF)." (PMID 40628732, 2025). "Wild-type LUAD demonstrated a higher number of tumor-infiltrating CD8+ T-cells, while in tumors with EGFR and ALK alterations, the number of CD8+ T-cells was much lower, and KRASm LUAD was heterogeneous in terms of tumor-infiltrating CD8+ cells count." (PMID 40809430, 2025). "To boost the anti-tumor activity of these cells, we designed a second-generation CAR structure targeting EGFR that incorporates the full human IL-7 sequence." (PMID 41450878, 2025). "This, in turn, results in the upregulation of PD-L1 in bladder cancer cells, the activation of the EGFR/ERK/C-Jun signaling pathway, and the facilitation of tumor immune escape." (PMID 40598593, 2025). "Building on this, the use of 3D spheroid models further highlighted the critical roles of both EGFR and IGF-IR in sustaining tumor growth and proliferation under 3D conditions." (PMID 40943584, 2025). "In a xenograft mouse model, the combination of EGFR and PI3K inhibitors reduced downstream signaling in the EGFR and PI3K pathways and inhibited the tumor growth in a statistically significant manner when compared to vehicle control." (PMID 40501689, 2025). "In terms of tumor response, the ORR was similar for the doublet plus BEV (n = 84) and doublet plus EGFR (n = 111) groups, with 67.9% (57/84) and 68.4% (76/111), respectively." (PMID 39941768, 2025).
tumor (continued). "These include miRNAs negatively regulating estrogen receptor α (ERα) or its coactivator/corepressor proteins, as well as miRNAs controlling signaling proteins in the ERα cascade (HER2, EGFR, Akt, MAPK) and tumor suppressors." (PMID 41403733, 2025). "Collectively, these findings support the conclusion that effective tumor control requires synergistic interaction between immunogenic tumor modulation by DTIC and ACT with EGFR mCAR T cells, following CPA-mediated lymphodepletion." (PMID 41516067, 2025). "To further assess potential on-target, off-tumor effects, we analyzed CD155 expression patterns alongside reference genes (EGFR, ERBB2, and ROR1), which are currently being investigated in clinical trials for CAR-T therapies." (PMID 40478751, 2025). "PRMT1 knockdown, combined with EGFR or KRASG12C inhibitors, decreased persistence and delayed cancer cell regrowth across cell line models and significantly prolonged tumor regression in xenograft models." (PMID 39699269, 2025). "In summary, cancer cells with activated and mutant EGFR may inhibit NK cell infiltration and cytotoxicity by expressing certain cytokines, and reduce the expression of ligands for NK cell activation receptors in cancer cells, contributing to tumor‐mediated immune escape." (PMID 40859900, 2025). "Tumor-to-background ratio (TBR) and mean fluorescence intensity (MFI) were quantified, and EGFR expression was analyzed by Western blot, reverse transcription quantitative polymerase chain reaction, and immunohistochemistry." (PMID 41346398, 2025). "Because tarloxotinib acts by inhibiting the epidermal growth factor receptor (EGFR or HER) family proteins, its effectiveness depends on the presence of HER1–4 in tumor cells." (PMID 40710312, 2025). "Future directions should emphasize rational design of dual-targeting nanocarriers, employing ligands for both BBB penetration (e.g., angiopep-2, transferrin, lactoferrin) and tumor specificity (e.g., RGD peptides, EGFR, folate)." (PMID 41009025, 2025). "EGFR signals to the ERK pathway and staining of tumor sections for phosphorylated ERK (pERK) was higher in PDO 5 tumors." (PMID 39639170, 2025). "Over recent years a number of additional scores have been published, including the tumour-specific BLESS and CAIL scores, and further “one-size-fits-all” scores such as SELECT, EGFR-LENT and modified-LENT." (PMID 40524925, 2025). "Cucurbitacin B degrades EGFR and downregulates the CIP2A/PP2A/AKT axis, inhibiting growth and invasion of gefitinib-resistant NSCLC and reducing xenograft tumor volume." (PMID 40943297, 2025). "Compared to tumors harboring wild-type EGFR, EGFR-driven NSCLC tumors exhibit low tumor immunogenicity, including reduced TMB, fewer neoantigens, impaired T cell clonality, and lower PD-L1 expression." (PMID 40733125, 2025). "The impairment of SCAP N‐glycosylation in GBM cells with activated EGFR signaling inhibits SREBP1 activation, reduces tumor growth of orthotopic GBM xenografts, and extends mice survival." (PMID 38105543, 2025). "Epidermal growth factor receptor and GDF-15 were excluded due to their irrelevance to her tumor genomics." (PMID 39786485, 2025). "The selected biomarkers (EGFR, ALK, KRAS, and PDCD1), demonstrated significantly higher expression in NSCLC tumor tissues compared to adjacent normal tissues (p < 0.01)." (PMID 40927719, 2025). "In this study, we present novel insights that IGF2BP2 is essential for EGFR and PIK3R1 mRNA stability and activation of the EGFR/PI3K/AKT axis in OSCC tumor cells and CAFs." (PMID 40362183, 2025).
tumor (continued). "This was achieved by testing the response of tumor cells, which were isolated from an MPE sample of a treatment‐naïve EGFR‐driven NSCLC patient, to targeted treatments and followed by correlation with genetic alterations and clinical outcomes." (PMID 40525275, 2025). "For instance, epigallocatechin gallate, a bioactive compound in green tea, inhibits tumor growth by disrupting CRC cell membrane rafts, thereby suppressing EGFR signaling." (PMID 41463331, 2025). "The knockdown of PRDX1 exerts a synergistic effect when combined with EGFR-TKI treatment, potently suppressing tumor growth." (PMID 40303499, 2025). "Effective anti-tumor responses were obtained following the simultaneous use of the Notch inhibitor GSI (DBZ) and the EGFR inhibitor (erlotinib); optimal results were obtained by lowering the dosage of both inhibitors but using them at the same time." (PMID 40429321, 2025). "In the leptomeningeal carcinomatosis mouse model, the combined inhibition of EGFR and WEE1 significantly suppressed tumor growth." (PMID 40518016, 2025). "In EGFR wild-type cases, univariate COX regression analysis showed that tumor size, distant metastases, HLF expression, and the number of CTCs were correlated to progression-free survival." (PMID 40124619, 2025). "Preclinical studies demonstrated potent antitumor activity in EGFR-expressing xenograft models through the selective delivery of MMAE, resulting in targeted tumor cell death while potentially minimizing systemic toxicity." (PMID 41375018, 2025). "Agents such as EGFR inhibitors and BRAF inhibitors effectively block critical signaling pathways in Tumor Cells, thereby suppressing their growth and survival." (PMID 41333481, 2025). "AEE-788 is a dual EGFR/HER2 and VEGFR inhibitor developed to suppress tumor growth and angiogenesis; it also inhibits ERBB4 (HER4) with an IC50 of 0.16 μM, suggesting potential modulation of ERBB4 signaling." (PMID 41256885, 2025). "Next, we detected the protein expression levels of SYVN1 and EGFR, as well as the correlation between SYVN1 expression and the progression of NSCLC in pairs of tumor specimens." (PMID 40877231, 2025). "SMART-Exos displaying bispecific antibodies (anti-CD3/anti-EGFR or anti-CD3/anti-HER2) enable simultaneous T cell activation and redirection toward tumour cells, and CD40L-expressing exosomes further boost dendritic cell maturation and cytokine secretion." (PMID 41181109, 2025). "Pyrotinib is an irreversible pan-HER inhibitor independently developed in China, which permanently binds to the ATP-binding sites of EGFR/HER1, HER2, and HER4 to block dimerization and downstream signaling, thereby inhibiting tumor growth." (PMID 40136352, 2025). "Although the majority of EGFR-mutant NSCLC patients benefit from treatment with EGFR-TKIs, acquired resistance is inevitable, thus leading to tumor recurrence and metastasis." (PMID 40463905, 2025). "The interplay of EGFR, L1CAM, MAPK, and DAP12 signaling pathways is crucial in TN BC, as their activation can drive tumor proliferation, invasion, and resistance to therapy in this aggressive subtype." (PMID 40894036, 2025). "Meanwhile, EGFR‐amplified tumors exhibit higher rCBV and elevated relative oxygen extraction fraction (OEF), indicating increased tumor cell invasion and angiogenesis." (PMID 40197845, 2025). "A particularly relevant target for aptamer-based diagnostics is the epidermal growth factor receptor (EGFR), a pivotal biomarker and therapeutic target in oncology with substantial implications in tumour progression and prognosis." (PMID 41149351, 2025). "EGFR, ERBB2, and FGFR1 are known to promote tumor growth and survival independently of AR signaling." (PMID 40429793, 2025). "Other CAR T targets under clinical evaluation include EGFR [NCT02980315], MUC1 [NCT03013712], CD44v6 [NCT04729543, NCT04097301], PD-L1 [NCT05117138], and CSPG4 [NCT06096038], reflecting efforts to overcome tumor heterogeneity and immune evasion." (PMID 40940995, 2025).
tumor (continued). "The anti-EGFR ESP, affibody molecules, demonstrated successful imaging of EGFR in preclinical tumor models." (PMID 41226646, 2025). "This approach increased selectivity for EGFR-high SKOV3 cells over EGFR-low MCF7 cells or healthy donor fibroblasts, and in triple coculture assays preferentially eliminated tumor cells while sparing fibroblasts." (PMID 41584599, 2025). "We identified 12 tumor CNs, e.g., CN3 with proliferative, EGFR+ hypoxic, and CK7+ tumor cells, CN7 consisting of hypoxic cells, and CN8 comprising immune-evasive and epithelial-low phenotypes." (PMID 39437149, 2025). "We analyzed tumor regions of 82 formalin‐fixed paraffin‐embedded (FFPE) tissue sections with 6, 23, 31, and 22 samples from the EML4–ALK, EGFR, KRAS, and WT sample groups, respectively." (PMID 40621945, 2025). "Using systems pharmacology, we identified 50 anti‐HCC core targets, including EGFR, c‐Myc, ERBB2, ESR1, CCND1, and HSP90AA1, all of which play critical roles in tumor initiation, proliferation, angiogenesis, and resistance mechanisms." (PMID 40727254, 2025). "Genetic alterations in oncogenic drivers such as EGFR, ALK, KRAS, BRAF, MET and others can modify immunogenicity and impact the tumor microenvironment (TME)." (PMID 40809430, 2025). "Combining GPC3 with EGFR, third-generation GPC3-EGFR CAR-T cells have been designed, showing enhanced proliferation and cytotoxicity while minimizing non-tumor toxicity." (PMID 40303292, 2025). "Nevertheless, there is still a lack of studies focusing specifically on the malignant epithelial cells in EGFR-mutant LUAD, which limits the development of more specific prognostic models and therapeutic prediction tools derived from the tumor itself." (PMID 41164195, 2025). "In tumor cells, PD-L1 glycosylation is promoted by EGF receptor (EGFR) activation, linking oncogenic signalling pathways to PD-L1 expression in tumors." (PMID 41425548, 2025). "EGFR undergoes nuclear translocation upon activation of AXL and AXL knockdown facilitates inhibition of tumor proliferation by modulating EGFR activity." (PMID 40560045, 2025). "EGFR activation has been shown to interact with inflammatory pathways such as NF-κB and IL-6/STAT3, leading to enhanced tumor proliferation, angiogenesis, and an immunosuppressive microenvironment." (PMID 41268168, 2025). "Overall, GOLM1 recruitment of Rab11 and EGFR/RTK led to EGFR-mediated signalling and tumour migration." (PMID 40293576, 2025). "Their study suggests that M2-type TAMs promote the EMT process by activating the EGFR/ERK1/2 signaling pathway, thereby enhancing tumor growth." (PMID 40136652, 2025). "For instance, cetuximab and panitumumab, both monoclonal antibodies targeting the epidermal growth factor receptor (EGFR), have been widely used in patients with RAS wild-type tumours." (PMID 40374593, 2025). "As a reference for SNIP, the EGFR and MKI67 levels were significantly higher in tumor tissues than in paired normal tissues." (PMID 39744163, 2025). "STMN1 can enhance the radioresistance of tumor cells by increasing autophagy, and it can mediate drug resistance in tumors through the AKT and EGFR‐related pathways." (PMID 40013670, 2025). "BG-conjugated antibodies or fragments against CD20, EGFR, or HER2 activated CAR T cells in vitro and inhibited tumour growth in an HER2 xenograft model in vivo." (PMID 41465327, 2025). "The data demonstrate that no-ReDOS dosage consistently improves PFS, especially in patients with a history of anti-EGFR therapy, older adults, individuals with right-sided or rectal primaries, or RAS wild-type tumours." (PMID 41154373, 2025). "The bsAbs exhibited stronger tumor cell binding capacity, more effectively EGFR signaling blockade, and more potent ADCC effects compared to cetuximab in B7H3 and EGFR double-positive cells." (PMID 41291854, 2025).